MIR941-2 (microRNA 941-2)
Synonyms: hsa-mir-941-2; MIRN941-2
Gene: MicroRNA gene on chromosome 20 (63,919,505 to 63,919,576, forward strand). Ensembl gene ENSG00000216141.
Homologues: Paralogues in human: MIR941-3 (22% identical), MIR941-4 (22% identical), MIR941-5 (22% identical).